BRCA1 (BRCA1 DNA repair associated)
Diseases named in the same sentence as BRCA1 in open-access papers (continued):
Sharing a sentence is not in itself a finding about the gene and the disease.
breast cancer (continued). "To propose candidate neoantigens for generalized breast cancer vaccine development, in both BRCA1-positive and BRCA1-negative samples, we looked at the top recurrent somatic mutations exclusively at coding regions." (PMID 36298462, 2022). "Consistent with our results, high levels of p65/p66 isoforms were reported to be expressed during BRCA1 depletion-driven EMT and two human basal-like breast cancer cell lines, further underscoring the importance of NUMB p65/p66 isoforms in mammary epithelial cells tumorigenesis." (PMID 35457181, 2022). "Using the breast cancer study as an example, it was found that the known eight famous genes—BRCA1, BRCA2, PALB2, BARD1, RAD51C, RAD51D, and ATM—in breast cancer research and practice actually lead to very low accuracy in predicting breast cancer status at the stage of diagnosis." (PMID 36298522, 2022). "Several genes in breast cancer exhibit CpG island hypermethylation and in several instances, abnormal activity of DNA methyltransferases led to the hypermethylation and silencing of HOXA5, TMS1, p16, RASSF1A, and BRCA1 genes of tumor suppressor behavior." (PMID 36185256, 2022). "The relatively high frequency of BRCA1/2 in PROCAS controls of 0.56% does not appear to be due to bias as 1st degree breast cancer family history was not more frequent in subjects who provided a DNA sample." (PMID 33763779, 2022). "However, most carriers of BRCA1 and BRCA2 with TN breast cancer in stage I benefited from RRBM-RRBSO or just RRBSO." (PMID 36580360, 2022). "Bioinformatic analyses did not reveal the correlations between iNOS, mutated BRCA1/2, and overexpression of HER2 in breast cancer datasets." (PMID 35740092, 2022). "We evaluated the potential improvement in prediction performance and utility for clinical decision-making of the updated models for both BRCA1/2 carriers as the general (non-tested) breast cancer population (PredictCBC-2.0)." (PMID 36271417, 2022). "Because most BRCA1 cases of breast cancer are ER- and most BRCA2 cases are ER+, the frequency of ER+ tumors among the overall BRCA breast cancer patients depends on the relative contribution of the gBRCA2 incidence in unselected breast cancer patients." (PMID 35805038, 2022). "Most of previous studies regarding BRCA1/2 LGR have primarily focused on ovarian and breast cancer." (PMID 36147908, 2022). "Equol induced the promoter hypomethylation of TSGs BRCA1 and BRCA2 in breast cancer cells." (PMID 37077808, 2022). "It is known that carriers of BRCA1 PVs tend to develop ER-/PR-/HER2-, i.e. triple negative breast cancers (TNBC), while carriers of BRCA2 PVs tend to develop ER + /PR + breast cancers, similar to sporadic forms lacking germline predispositions." (PMID 35135604, 2022). "We hypothesize that there are some cross-talk signaling pathways between iNOS expression and the expression of breast cancer protooncogenes: HER2, BRCA1, and BRCA2." (PMID 35740092, 2022). "Therefore, in breast cancer patients with reduced HspBP1 expression, DNA damage accumulates due to suppressed BRCA1 function, and the ability to remove these damaged cells is decreased as a result of suppressed Hsp70 proapoptotic functions which may synergistically trigger breast cancer progression." (PMID 35387978, 2022). "This study included 2346 women, 1844 of whom had a mutation in the BRCA1 gene and 502 in the BRCA2 gene, all without breast cancer." (PMID 35805026, 2022). "The study demonstrated that TNBC was closely related to BRCA1 mutations, compared to patients with BRCA2 mutations carriers or non-carriers, breast cancer patients with BRCA1 mutation are more likely to have TNBC." (PMID 36242046, 2022). "A total of 3.6% of patients carried a pathogenic/likely pathogenic variant in a known breast cancer susceptibility gene: 1.2% in BRCA1, 0.6% in each of BRCA2, ATM, CHEK2 and PALB, none of whom had any family history of breast cancer." (PMID 35039564, 2022).
breast cancer (continued). "Often young women affected with BRCA1/2 positive breast cancer have not finished or even not started their childbearing before the onset of the disease." (PMID 35062994, 2022). "The evaluation over efficacy of gedatolisib, a PI3K and mTOR inhibitor, in combination with talazoparib (PARP inhibitor) in TNBC or BRCA1/2 positive breast cancer with HER2 negative was conducted in a phase II clinical trial." (PMID 35243562, 2022). "BRCA1 and BRCA2 are potential biomarkers for HRD in ovarian and breast cancer." (PMID 35785170, 2022). "In contrast to BRCA1, FOXP3 is a transcriptional inducer of miR-155 in breast cancer cell lines." (PMID 35328651, 2022). "In breast cancer, UBE2T promoted tumorigenesis via the ubiquitin-mediated degradation of BRCA1." (PMID 36357897, 2022). "The median age of breast cancer diagnosis was 43, 44, and 46 in BRCA1 carriers, BRCA2 carriers, and noncarriers; the median age of ovarian cancer diagnosis was 51, 54, and 52 in BRCA1, BRCA2 carriers, and noncarriers, respectively." (PMID 35378767, 2022). "Among 4916 non-Jewish breast cancer cases undergoing full BRCA1 and BRCA2 testing, only two co-occurrences of BRCA1 and BRCA2 PVs has occurred including the single case reported in this study." (PMID 33758026, 2022). "Furthermore, compounds 4, 5, 8a, 10b, and 11b were evaluated as in vitro antiproliferative agents against the mutant BRCA1 (MDA-MB-436, breast cancer) compared to Olaparib as a positive control." (PMID 35956876, 2022). "Interestingly, the BRCA1/2‐positive rate was similar among different age groups in the OV cohort, which was different from the BROV cohort, as well as the BRCA‐positive breast cancer patients in our previous study." (PMID 35608067, 2022). "The selected participants showed a positive family history of breast cancer, yet they harbor intact BRCA1/2 genes with no aberrations." (PMID 35650591, 2022). "While a study of over 30,000 women with breast cancer found no significant increase in risk of breast cancer in women with MUTYH, a recent study of 165 women with BRCA1/2-negative IBC found that MUTYH was the most commonly mutated gene (3.6%)." (PMID 36091166, 2022). "For example, the POSH study showed that young-onset breast cancer patients with symptomatic breast cancer have similar overall medium-term survival comparing BRCA1/2 carriers to non-carriers." (PMID 35715636, 2022). "Reversion mutations within multiple genes in the HRR pathway, including BRCA1, BRCA2, RAD51C, RAD51D, and PALB2, have been reported in ovarian, prostate, and breast carcinomas as a mechanism of acquired or primary resistance to platinum-based chemotherapy and PARP inhibitors 7-18." (PMID 35281878, 2022). "This topic remains controversial for the reported differences in BRCA1 and BRCA2 pathogenic variant carriers and for the different effects of pregnancy on breast cancer risk according to age also in the general non-BRCA carrier population." (PMID 34503502, 2021). "A comparison of baseline and progressed tumor volumes in treated (red line) and non-treated (black line) Brca1-mutant tumor-bearing mice showed that mammary tumor volumes increased 2.39-fold after irradiation and more than 7 times in the absence of treatment." (PMID 33767581, 2021). "Undifferentiated (G3) basal-like ductal breast cancers (triple-negative) are the most recurrent in BRCA1 carriers, while fewer data are available about BRCA2 carriers, although BRCA2 tumors seem to be more similar to sporadic breast cancer both for histological and molecular characteristics." (PMID 34572941, 2021).
breast cancer (continued). "Moreover, based on the sequencing genomic DNA (from 1,370 cases and 1,635 controls), approximately 5.6% of patients are the carriers of a pathogenic variant in breast cancer gene 1 (BRCA1), BRCA2, partner and localizer of BRCA2 (PALB2), or tumor protein 53 which are the main penetrant genes of BC." (PMID 36046117, 2021). "It is estimated that 20–40% of BRCA1/2 patients who would never develop breast cancer are grossly overtreated with preventive mastectomies." (PMID 32725533, 2021). "A previous study on the expression of BAP1 tumor suppressor gene in 1222 patients with TCGA breast cancer data reported that the expression of BAP1, which enhances BRCA1-mediated suppression of cell proliferation through BRCA1 stabilization, is highly correlated with USP19 expression." (PMID 34439131, 2021). "Up to now, in breast cancer patients, the investigation of BRCA1/2 gene epigenetic silencing has not routinely been included into the clinical algorithm of patients’ profiling and therapeutic approach." (PMID 33808555, 2021). "We have previously shown that a pathogenic RAD51D variant in a family with three women with ovarian cancer and four with breast cancer(MS = 55) fully segregated with disease and that BRCA1/2 testing, including RNA analysis was negative." (PMID 34439310, 2021). "In breast cancer, miR-182 overexpression induces HRD by targeting BRCA1." (PMID 34711195, 2021). "In BRCA1 carriers, HRs of breast cancer after RRSO were not significant at 0.96 (95% CI, 0.73 to 1.26), nor were they significant in BRCA2 carriers (HR, 0.65; 95% CI, 0.37 to 1.16)." (PMID 34565426, 2021). "For the well-known breast cancer biomarkers, only HER2 status was statistically significantly associated with high risk (p = 0.010), but not others (BRCA1, BRCA2, ER, PR, p > 0.05)." (PMID 34650974, 2021). "The fact that the control mice did not develop any mammary tumor while 50% or more of B1p53, P2p53, and B2p53 mice did clearly demonstrate the tumor-suppressive activities of BRCA1, PALB2, and BRCA2 in the mammary gland." (PMID 33893322, 2021). "In comparison to non-carriers, 63% of BRCA1 positive cases reported family history of breast cancer and 56% of BRCA2 cases had family history of other cancers (p = 0.001)." (PMID 34206661, 2021). "In this cohort study, 8396 patients with operable primary breast cancer (187 BRCA1 carriers, 304 BRCA2 carriers, and 7905 noncarriers) underwent BCT, mastectomy with radiotherapy, or mastectomy alone." (PMID 33890992, 2021). "In the case of BRCA1 having ~ 24 exons, 32 isoforms were identified, including 18 novel ones found in the control lymphoblastoid cells but not in breast cancer tissues." (PMID 33931666, 2021). "Nevertheless, BRCA1 carriers were more likely to be triple negative breast cancer compared to BRCA2 carriers (p=0.002) and BRCA2 carriers were more likely to be luminal B breast cancer tumors (p=0.000078)." (PMID 34490083, 2021). "In contrast to BRCA1, PINK1/Parkin was expressed at lower levels in breast cancer patients." (PMID 33888730, 2021). "SP18–28 incubation resulted in reduced clonogenic survival of MDA-MB-436 and SUM149PT BRCA1 mutant breast cancer cell lines but not of BRCA1-proficient MCF7 breast cancer or MCF10A and RPE1 nontumorigenic cell lines." (PMID 33608267, 2021). "Their upregulation has been observed in several cancer cell lines, including breast cancer cells lacking BRCA1." (PMID 34599155, 2021). "However, BRCA1 carriers were more likely to have triple negative breast cancer (p=0.002) and BRCA2 carriers were more likely to have luminal B breast cancer tumors (p=0.000078)." (PMID 34490083, 2021).
breast cancer (continued). "Interestingly, HER4 mRNA expression has been found to correlate with BRCA1 mRNA expression in human breast cancer samples and requires BRCA1 activity for NRG-1-mediated breast cell growth inhibition, as shown by in vitro and in vivo BRCA1 knockdown studies." (PMID 34885957, 2021). "For women aged 50 years or older at breast cancer diagnosis, RS often exceeded the chemotherapy benefit threshold (≥26) with BRCA1 (71.7% vs 14.4% with none; P <.001), PALB2 (37.1%; P = .001), and BRCA2 (44.3%; P < .001) PVs." (PMID 33426465, 2021). "for any PV, including BRCA1/2, was in grade 1 estrogen receptor (ER)+/HER2− breast cancers." (PMID 34439310, 2021). "Although it is currently unknown whether miRNA-146a-5p possesses oncogenic properties in GBM cells, results obtained in breast cancer tissue and MCF-7 cell line support this role through the BRCA1 pathways." (PMID 33610185, 2021). "BRCA1-related breast cancers were more likely grade 3 and oestrogen receptor negative (ER−) than cases in the high-risk BRCA negative cohort as expected (p < 0.0001 for both)." (PMID 34312777, 2021). "For instance, among two cohorts of breast cancer patients, the TMB was 2.0 to 2.6 times higher in patients with a BRCA1 or BRCA2 mutation as compared to those without a BRCA mutation." (PMID 34067105, 2021). "Although PALB2 encodes a protein involved in DNA double-strand break repair carried out by BRCA2, tailored therapies for breast cancer patients carrying PVs in genes other than BRCA1/2 have not yet been established." (PMID 33718150, 2021). "The new technologies discussed here allow a similar course of action for the much larger set of families with breast cancer history who are not carriers of BRCA1 or BRCA2." (PMID 34440279, 2021). "Through Next Generation sequencing (NGS), we analyzed all of the coding regions and the exon–intron junctions of BRCA1 and BRCA2 genes—the two most important genes in hereditary breast cancer—in fifty-one women from Burkina Faso with early onset of breast cancer with or without a family history." (PMID 34717758, 2021). "Defective PARylation of BRCA1 gives rise to uncontrolled HR and genome instability, resulting in genomic abnormalities similar to those observed in the absence of BRCA1 in some breast cancers." (PMID 33922595, 2021). "It has been demonstrated that patients with germline BRCA1/2mut did not portend worse breast cancer-specific outcomes compared to non-carriers; however, this study was not analysed in accordance with ER status." (PMID 33671468, 2021). "In this report, we show that breast cancer patients whose tumors show high levels of cyclin E expression also have a higher prevalence of DNA repair gene (e.g., BRCA1/2) alterations compared to those patients without cyclin E overexpression." (PMID 33916118, 2021). "This new evidence includes the identification of mouse mammary tumour virus (MMTV) in sporadic breast cancers but not in BRCA1 breast cancers." (PMID 34108009, 2021). "Recent studies from the United Kingdom and Australia have shown that multigene testing (BRCA1, BRCA2 and PALB2, and BRCA1 and BRCA2, respectively) for all breast cancer patients would be cost-effective when compared with current eligibility criteria based on personal and family-history testing." (PMID 33113089, 2021). "Although eIF3e silencing results in HR defect also in breast cancer cells, we found that these eIF3e-depleted cells were not sensitive to veliparib treatment, in contrast to BRCA1-depleted cells." (PMID 33868586, 2021). "The variants detected in the present study were not among the most frequent mutations in BRCA1 and BRCA2 in Brazilian patients with breast cancer." (PMID 34287479, 2021). "BRCA1/2 carriers exhibited significantly worse RFS than non-carriers, with three-fold increased risk of contralateral breast cancer or locoregional recurrence." (PMID 34206661, 2021).
breast cancer (continued). "In Poland, 20 founder mutations in BRCA1, BRCA2, CHEK2, PALB2, NBN, RECQL are responsible for the majority of hereditary breast cancer cases in women, but the utility this genes panel has not been tested in men." (PMID 34461861, 2021). "The cumulative risk of breast cancer was higher in both BRCA1 and BRCA2 male heterozygotes compared to those without a BRCA1/2 pathogenic variant at all ages." (PMID 33959510, 2021). "A prospective cohort study showed that RRSO reduced all-cause mortality in both pre- and postmenopausal women; however, RRSO significantly reduced the risk of breast cancer for BRCA2 pathogenic variant carriers, but not for BRCA1 pathogenic variant carriers." (PMID 34071148, 2021). "Overall mortality was significantly reduced in both subgroup analyses for patients with a history of BRCA1- and BRCA2-mutated breast cancer and no history of breast cancer." (PMID 32862296, 2021). "In HR pathway, other miRNAs play an important role in DSB repair: miR-138 targeting H2A.X in osteosarcoma cells, miR-146a and miR-146b-5p targeting BRCA1 in breast cancer, miR-1 targeting BRCA1 in prostate tumor cell lines, and miR-1245 targeting BRCA2 in breast cancer cell lines." (PMID 34094980, 2021). "All went on to have genetic testing, 100% (3/3) had BRCA1/2 testing only, and there were no breast cancer panel or predictive tests arranged." (PMID 33637119, 2021). "Lack of BRCA1/2 status and Ki-67 data for many breast cancer patients is another limitation of the current study." (PMID 34300003, 2021). "Furthermore, higher BRCA1 expression and lower PINK1/Parkin expression were significantly correlated with poor recurrence-free survival rate in breast cancer patients." (PMID 33888730, 2021). "The level of autophagy in MCF7 breast cancer (BC) cells can be increased by mTOR inhibitor, rapamycin (RAPA), delayed the attendance of Rad51 and BRCA1 protein localization, and prolonged the expression of damage characteristic sensor γ-H2AX, resulted in the accumulation of DSB damage." (PMID 34321364, 2021). "Currently, SA patients with the luminal-type breast cancer are not routinely selected for BRCA1/2 testing as is the case for triple-negative disease." (PMID 34660253, 2021). "In Morocco, BRCA1 and BRCA2 mutations have been extensively investigated for breast cancer but not so for prostate cancer." (PMID 34242281, 2021). "Although initial genetic testing results in the KOHBRA study revealed a VUS in 676 patients (278 patients for BRCA1 and 453 patients for BRCA2) out a total of 2,403 breast cancer patients (28.13%, 676/2,403), re-evaluation revealed a lower frequency of VUSs (8.03%, 193/2,403)." (PMID 33875706, 2021). "Therefore, it is possible that while BRCA1/2 mutation status may play an important role in predicting PARPi response in metastatic patients, it may not necessarily have the same significance in early breast cancer patients." (PMID 34959671, 2021). "In contrast, previous studies reported a high BRCA1/2 mutation frequency of 15.2–15.4% and a non-BRCA mutation rate of 15.4% in Chinese male breast cancer patients." (PMID 34917121, 2021). "On the other hand, the risk estimated from BCRAT is not dependent on the likelihood of being a BRCA1 or BRCA2 mutation carrier, and the relative risks attributed to family history of breast cancer remain constant with age of the consultee." (PMID 34680343, 2021). "Testing comprised of 23% (3/13) BRCA1/2 testing only and 76% (10/13) breast cancer panel testing, there were no predictive tests performed." (PMID 33637119, 2021).